HIP1 (huntingtin interacting protein 1)
Diseases named in the same sentence as HIP1 in open-access papers (continued):
Sharing a sentence is not in itself a finding about the gene and the disease.
rheumatoid arthritis (2 papers, 2020 to 2024). A chronic, systemic autoimmune disorder characterized by inflammation in the synovial membranes and articular surfaces. "Similar results were reported in the context of fibroblast-like synoviocyte models of rheumatoid arthritis, one of the most common autoimmune diseases, where HIP1 expression was shown to be required for receptor tyrosine kinase (RTK) stabilization on the cell surface." (PMID 32069895, 2020).
asthma (1 paper, 2024). "However, there is no distinct association between HIP1 and asthma." (PMID 38750426, 2024). "This analysis revealed multiple genomic loci associated with COVID-19 severity with or without asthma comorbidity, including DSP, HIP1 and RP1 genes." (PMID 38750426, 2024). "The GWAS comparing individuals with severe COVID-19 with asthma to those without asthma revealed four genetic variants in transmembrane protein with EGF like and two follistatin like domains 2 (TMEFF2) and huntingtin interacting protein-1 (HIP1) genes." (PMID 38750426, 2024).
astrocytoma (1 paper, 2017). "NUSAP1 also upregulated the expression of the downstream targets of HH pathway including PTCH1, HIP1, CCND1, CCNE1 and HDAC1 in astrocytoma." (PMID 28899410, 2017).
chronic myelomonocytic leukemia (1 paper, 2020). A myelodysplastic/myeloproliferative neoplasm which is characterized by persistent monocytosis, absence of a Philadelphia chromosome and BCR/ABL fusion gene, fewer than 20 percent blasts in the bone marrow and blood, myelodysplasia, and absence of PDGFRA or PDGFRB rearrangement. "Chiefly, HIP1, a cofactor in clathrin-mediated vescicle trafficking, was firstly found to be implicated in cancer as part of a chromosomal translocation in patients with chronic myelomonocytic leukemia." (PMID 32069895, 2020).
COVID-19 (1 paper, 2024). A disease caused by infection with severe acute respiratory syndrome coronavirus 2. "This indicates that HIP1 may be implicated in COVID-19 through its interaction with clathrin." (PMID 38750426, 2024).
endophthalmitis (1 paper, 2025). An infectious process affecting the internal structures of the eye. "In the patient sera, MMP-9, MPO, Calprotectin, NGAL, SAA (HVIP1), and MCP-1 (HIP1) were all significantly elevated in endophthalmitis samples, which was unexpected as pathology was thought to be localised with minimal systemic effects." (PMID 40563988, 2025).
glioma (1 paper, 2025). A benign or malignant brain and spinal cord tumor that arises from glial cells (astrocytes, oligodendrocytes, ependymal cells). "In glioma, miR-615-5p played a significant role in tumor growth by targeting huntingtin-interacting protein-1 (HIP1)." (PMID 39789663, 2025).
infantile spasms (1 paper, 2022). A rare epilepsy syndrome characterized by onset of epileptic spasms in infants between 2 and 12 months of age, and rarely up to 24 months. "In addition, three out of 14 patients with deletions including HIP1 and YWHAG, but not MAGI2, had infantile spasms, excluding one patient whose seizure type was not specified." (PMID 35481155, 2022).
inflammatory myofibroblastic tumor (1 paper, 2015). A multinodular intermediate fibroblastic neoplasm that arises from soft tissue or viscera, in children and young adults. "Among them, huntingdon-interacting protein (HIP1)-ALK and RAN-binding protein 2 (RANBP2)-ALK, which have been reported to exist in NSCLC and inflammatory myofibroblastic tumors, respectively, show clinical responses to crizotinib." (PMID 26295973, 2015).
oligodendroglioma (1 paper, 2021). A well-differentiated (WHO grade II), diffusely infiltrating neuroglial tumor, typically located in the cerebral hemispheres. "Given that HIP1 is overexpressed in multiple cancer types, including oligodendrogliomas, it has been proposed as a tumour marker." (PMID 33368549, 2021).
prostate tumors (1 paper, 2020). "Consistent with this evidence, primary prostate tumors lacking HIP1 expression were characterized by reduced frequency of disease progression, in terms of biochemical relapse, after radical prostatectomy." (PMID 32069895, 2020).
renal clear cell carcinoma (1 paper, 2022). "Furthermore, analysis of renal clear cell carcinoma showed that GNB1 was correlated with WASP family member 2 (WASF2), Neuropilin-1 (NRP1) and huntingtin interacting protein 1 (HIP1) of the vascular endothelial growth factor (VEGF) signaling pathway." (PMID 35193469, 2022).
respiratory failure (1 paper, 2012). The significant impairment of gas exchange within the lungs resulting in hypoxia, hypercarbia, or both, to the extent that organ tissue perfusion is severely compromised. "Disruption of the membrane-bound Hedgehog interacting protein-1 (HIP-1) results in upregulation of Hh signaling, causing neonatal lethality from respiratory failure: Hip-1 directly binds mammalian Hh proteins and moderates their signaling." (PMID 22871018, 2012).
Sepsis (1 paper, 2020). Sepsis is defined as life-threatening organ dysfunction caused by a dysregulated host response to infection. "Of the 317 sepsis-associated genes regulated by these DEMs, five (HIP1, GJC1, MDM4, IL6R, and ERC1) were designated as hub genes based on their degrees and other centrality measures (degree, betweenness, and closeness) from the significant modules." (PMID 33182754, 2020).
testicular degeneration (1 paper, 2019). "The least affected HIP1 KO strain suffered only from testicular degeneration, a phenotype also present in other HIP1 KO mouse lines which was later attributed to defects in spermatid maturation and decreased sperm motility." (PMID 31671891, 2019).
tuberculosis (1 paper, 2022). A chronic, recurrent infection caused by the bacterium Mycobacterium tuberculosis. "The HIP1 gene (chromosome 25) plays a role in the susceptibility to tuberculosis, which is an infection that is very similar to MAP at the cellular level." (PMID 36243688, 2022).
cancer (15 papers, 2009 to 2025). A tumor composed of atypical neoplastic, often pleomorphic cells that invade other tissues. "The most significantly DEGs in both HIP1R and HIP1 analyses are involved in cancer cell behaviors and outcomes." (PMID 40214437, 2025). "HIP1 is also an endocytic protein and is overexpressed in a variety of human cancers." (PMID 34277631, 2021). "GLI1 and HIP1 expression was detected in 9 of 34 (~26%) and 7 of 34 (~21%) cancers respectively." (PMID 19943941, 2009). "HIP1 expression was only detected in 2 specimens which expressed PTCH1 or Gli1, indicating that HIP1 is not highly expressed in ovarian tissues or is silenced in cancers as reported in other studies." (PMID 19943941, 2009).
tumor (12 papers, 2009 to 2025). "Overall, this evidence supports the hypothesis that at least part of miR-1272 tumor-suppressive effects are maybe ascribable to its ability to directly repress HIP1." (PMID 32069895, 2020). "In contrast, for the primary tumor cell line SW480, only 3 genes (HIP1, HSPH1, HTT) showed significant oscillations." (PMID 32295075, 2020).
infection (5 papers, 2014 to 2022). The state of being infected such as from the introduction of a foreign agent such as serum, vaccine, antigenic substance or organism. "Following the confirmation of attenuated HIP1 levels by Western blotting, we determined infectivity by measuring luciferase activity at 6-days post-infection." (PMID 34835114, 2021). "Our studies point to Hip1-dependent proteolysis as a novel regulatory mechanism that helps Mtb respond rapidly to changing host immune environments during infection." (PMID 24830429, 2014). "We have previously shown that the cell envelope in the hip1 mutant is altered such that infection of macrophages with this mutant induces a more rapid onset and significantly higher levels of proinflammatory cytokines compared to wild type Mtb infection." (PMID 24830429, 2014). "Our studies implicate Hip1-dependent proteolysis of its substrate as a novel regulatory mechanism in Mtb that helps the pathogen respond rapidly to changing host immune environments during infection." (PMID 24830429, 2014). "Our data supported a model in which contact between the hip1 mutant and macrophage cell surfaces, early in infection, triggered a more rapid and robust activation of TLR and inflammasome pathways in macrophages, which in turn ameliorated TB disease progression and immunopathology at later stages." (PMID 24830429, 2014). "To investigate the role of Hip1-dependent proteolytic cleavage of GroEL2 in infection of macrophages and its contribution to the hyperinflammatory phenotype of the hip1 mutant, we generated a hip1 mutant strain complemented with a secreted, cleaved form of GroEL2." (PMID 24830429, 2014). "The secreted hydrolase Hip1 has been shown to blunt the secretion of cytokines, including TNF, following infection." (PMID 34755600, 2021).
neurodegenerative disease (4 papers, 2009 to 2021). A disorder of the central nervous system characterized by gradual and progressive loss of neural tissue and neurologic function. "HIP1 protein levels distinguished MSA from all the other neurodegenerative diseases investigated, being overexpressed in PD, PSP and HD when compared to MSA." (PMID 33368549, 2021). "Our data provide the first evidence for changes in DNA methylation across brain regions in MSA, including in HIP1, LMAN2 and MOBP, all relevant to neurodegenerative diseases." (PMID 31535203, 2020). "Our results suggest that HIP1 and, to some extent MOBP, may be candidate markers in neurodegenerative diseases." (PMID 33368549, 2021).
neurological disease (4 papers, 2018 to 2023). "The role of HIP1 in neurological disease is supported by several functional studies." (PMID 35481155, 2022).
adenocarcinoma (1 paper, 2019). A common cancer characterized by the presence of malignant glandular cells. "Finally, patient E5011 presented HIP1‐ALK rearranged adenocarcinoma with metastases spreading to the lung, meningitis, and pericardium at diagnosis." (PMID 31651105, 2019).
HIP1 also shares sentences with these, for which no sentence is quoted: cognitive deficits (2 papers); Down syndrome (2); multiple system atrophy (2); neurodevelopmental disorder (2); Parkinson disease (2); Alzheimer disease (1); attention deficit-hyperactivity disorder (1); autism (1); autoimmune disease (1); basal cell carcinoma (1); bladder cancer (1); breast tumours (1); Costello syndrome (1); dementia (1); Failure to thrive (1); genetic generalized epilepsy (1); invasive ductal carcinoma (1); iron deficiency (1); leukodystrophy (1); malignant glioma (1); mastitis (1); metabolic disease (1); neuroblastoma (1); non-small cell lung carcinoma (1); Obesity (1); pheochromocytoma (1); salivary duct carcinoma (1); Seizure (1); spinocerebellar ataxia (1); Stroke (1).
A further 4 diseases each share a sentence with HIP1 in 1 paper.